TLR2 (toll like receptor 2)
Diseases named in the same sentence as TLR2 in open-access papers (continued):
Sharing a sentence is not in itself a finding about the gene and the disease.
infection (continued). "Previously, we could show that known inhibitors of TLR2 lead to a significantly increased microbial invasion into the infection model, due to a lack of activation of the antimicrobial defense mechanisms of derma fibroblasts." (PMID 35208698, 2022). "To investigate whether A. muciniphila can inhibit the expression of TLR-2 and TLR-4 in LX-2 cells, we coinfected live and pasteurized A. muciniphila with three different multiplicities of infection (MOIs 1, 10, and 100) and EVs in various concentrations (1, 10, and 50 μg/ml) for 24 h." (PMID 34549998, 2021). "Here, PMHs recognized HBV particles as pathogens via TLR2, without the process of infection." (PMID 34113355, 2021). "It was also demonstrated that the absence of TLR2 during experimental S. brasiliensis infection promoted increased dissemination after 14–28 days, suggesting a polarized Th17 response in an attempt to control the infection." (PMID 34867977, 2021). "Fungal recognition receptors commonly studied on MCs are TLR2/4 and Dectin-1.Upon activated by TLR/MyD88 or Syk pathway, MCs can produce specific cytokines and chemokines which can elicit a direct temporary immune response and recruit some neutrophils to the infection sites." (PMID 34149729, 2021). "IL-6 can issue a warning signal in response to both infection and noninfectious tissue damage which may be recognized by TLRs such as TLR2 and TLR4." (PMID 34336088, 2021). "Several studies have previously demonstrated that the activation of TLR2 and TLR4, as well as the subsequent activation of transcription factors leading to the production of inflammatory molecules, are important in the control of infection by various Leishmania spp." (PMID 34691019, 2021). "The disseminated bacteria were increased in TLR2 mice even without infection." (PMID 34322122, 2021). "Thus, TLR2-mediated NF-κB activation but not TLR2 axis-mediated infection appears to be DENV strain/genotype specific." (PMID 32576819, 2020). "Only TLR2-/-TLR5-/-Unc93b13d/3d mice failed to express significant IL-10 after Δhly infection." (PMID 32634175, 2020). "The functions of TLR2 on these monocyte subsets may also be dictated by the differential expression of CD14, CD16, TLR10, CD3620,55–58 and/or other receptors capable of modulating DENV infection and DENV-infection-mediated responses." (PMID 32576819, 2020). "While infection with Δhly induced significant IL-10 secretion from WT BMMs, Δhly induced almost no detectable IL-10 secretion in TLR2-/- BMMs, suggesting that bacterial lipoproteins are the major activators of IL-10 secretion in response to infection with Δhly." (PMID 32634175, 2020). "Indeed, various S. aureus-induced murine infection models demonstrate that lack of TLR2 leads to a more severe disease outcome, resulting in higher persistence of bacterial burdens in organs." (PMID 32404866, 2020). "Thus, in vitro DENV infection but not ex vivo infection leads to the selective upregulation of TLR2 on monocyte fractions." (PMID 32576819, 2020). "Thus, contrary to our initial expectations, our data indicate that TLR2 does not contribute strongly to the immune-pathological changes occurring during the subacute stage of infection with T. gondii, under our experimental conditions at least." (PMID 31404078, 2019). "Altogether, these results indicate that treatment with CL429, a TLR2 and NOD2 agonist, leads to increased production of cytokines and antibacterial mediators ex vivo, in the peritoneal cavity, the bone marrow and the spleen, which are remote from the site of infection." (PMID 31107928, 2019). "Considering that infection by IOE and E. muris produce distinct in-vivo phenotypes (fatal vs. mild disease, respectively), recognition by Ehrlichia involving TLR2 or NOD2 signaling in macrophages could be hypothetically correlated with the particular polarization into M1 or M2 types." (PMID 31575880, 2019).
infection (continued). "However, our results indicated that USP19-deficiency did not affect induction of downstream effector genes after infection with both RNA and DNA viruses or stimulation with TLR2 and TLR7/8 ligands in mouse primary immune cells." (PMID 31511519, 2019). "Expression of both TLR4 and TLR21, but not TLR2, is readily increased (6 h post infection) in cecal tissues in response to C. jejuni inoculation in 1-day-old birds, whereas in 2- and 4-week-old broiler chicks this is accompanied, however, by only a limited cytokine gene expression." (PMID 30234123, 2018). "Focusing on the modulation of immune responses by EVs in the acute phase of infection, only after stimulation with EVs from YuYu (DTU TcI) and CL-14 (DTU TcVI), peritoneal macrophages from C57BL/6 mice produced high levels of proinflammatory cytokines (TNF-alpha) and NO, via the TLR-2." (PMID 29727453, 2018). "Given that PD patients are prone to infections, this ability of sTLR2 would be advantageous when comparing with complete TLR blockade-based therapies, e.g., by combination of anti-TLR2 and -TLR4 antibodies, as these may have a detrimental effect on infection clearance." (PMID 30538643, 2018). "Since NK cells rarely express Dectin-1, TLR2, or TLR4 on their surface these experiments supported our hypothesis that DCs have a substantial supporting role in NK cell activation which may also play a role in vivo during infection with A. fumigatus." (PMID 30177958, 2018). "The role of the innate immune receptor Toll-Like Receptor 2 (TLR2) in the host response to P. gingivalis exemplifies this dissociation—sensing of infection and the inflammatory response are driven by TLR2, however, the response does not lead to killing of P. gingivalis." (PMID 28848717, 2017). "However, contrary to our expectations, TLR2 signaling had a negative rather than a positive effect on iNOS/NO expression at the early stage of infection (before 60 dpi), although this condition was changed at the later stage (120 dpi)." (PMID 28784165, 2017). "However, the relevance for kidney infection is not clear, since the lack of TLR2 did not change fibrosis and did not reduce inflammation in kidneys of mice 15 days post-infection with L. interrogans." (PMID 28270811, 2017). "However, no eggs were found in the faeces from both TLR2 wild-type and mutant mice after the infection." (PMID 28784165, 2017). "We next hypothesized that factors known to prime cells responding to infection, such as IFN-γ and Granulocyte-Macrophage Colony-Stimulating Factor (GM-CSF), may contribute to the ability of P. gingivalis to induce TLR2-dependent, MyD88-independent inflammatory signaling." (PMID 28848717, 2017). "The difference in the expression of EGFR during infection and activation of HGEC was a discrepancy that has also been observed in human monocytes, reflecting the fact that live bacteria signaled mostly through TLR-2 and TLR-4, while purified LPS-Pg acted through TLR-2." (PMID 28748038, 2017). "A recent report has shown that TLR2 deficiency had no impact on the i.d. route of OtK infection in C57BL/6 mice; however, i.p.-inoculated TLR2-/- mice were more resistant to lethal infection than wild-type controls, with major differences only at late/convalescence phases." (PMID 28742087, 2017). "Furthermore, it appears that lipophosphoglycan (LPG) is not the major mediator of TLR2 activation during infection with L. mexicana, as parasites lacking LPG (axenic amastigotes and LPG1−/− promastigotes) also resulted in exacerbated disease in TLR2−/− mice." (PMID 27716391, 2016). "The strong dependence on intact NF-κB signaling for L. pneumophila replication and the involvement of TLR2 in OMV recognition led us to test for expression of the anti-inflammatory microRNA 146a (miR-146a), as it has been shown to be involved in the response to infections." (PMID 27105429, 2016).
infection (continued). "Therefore, this natural high expression of TLR-2 by BALB/c may favor the IL-27 increase early after infection, lowering inflammation, and promoting infection." (PMID 27867384, 2016). "In order to analyze the role of TLR2 and TLR4 in the control of B. microti infection, WT B10, TLR2−/−, TLR4−/− and TLR2×4−/− mice were infected ip with a sublethal dose (105 cfu) of B. microti and bacterial load was determined in spleen and liver 3, 7, 14, and 21 days after infection." (PMID 28119856, 2016). "At later stages, all mice control infection and compensate for the lack of TLR2 and TLR4 by additional unknown mechanisms." (PMID 28119856, 2016). "Due to our inability to exclude redundancy between TLR1 and TLR6 in these infection models, we are unable to rule out the possibility that TLR2 may utilise either TLR1 or TLR6 co-receptor involvement in these settings." (PMID 27716391, 2016). "Moreover, lipoteichoic acids of S. aureus induce TLR2 signalling which leads to IRF1 upregulation and therefore also might contribute to the growth arrest during infection." (PMID 27834866, 2016). "Moreover, inactivation of TLR2 led to increased mortality in USA300 wild-type infected mice with no surviving animals 4 days after infection." (PMID 27470911, 2016). "This suggested that DV2-infection can trigger NFκB activation through pathway independent of TLR2." (PMID 26226614, 2015). "As expected, infection didnot significantly change the already elevated expression of TLR2." (PMID 25738770, 2015). "Concomitantly, the immunoregulatory effect of TLR2 stimulation by GPI-mucin in dendritic cells may also balance TLR9 and TLR7 activation by parasite DNA and RNA, respectively, at least in the initial phases of infection." (PMID 26834737, 2015). "Persistent unregulated TLR2 stimulation may result in perennial inflammation despite the absence of a specific infection." (PMID 25973436, 2015). "In addition, DV2-infected PBMC expressed higher level of TLR6 and TLR2 on day 3 post-infection but not day 1 and day 2 post-infection." (PMID 26226614, 2015). "The blocking of TLR2 or TLR4 did not affect alveolar survival during infection." (PMID 24489729, 2014). "Before infection, TLR2 knockout did not affect the development of Th1, Th2, Tc1, Tc2 cell subsets." (PMID 24376539, 2013). "Indeed, it was shown that L. (Viannia) panamensis infection results in up-regulation of TLR1, TLR2, TLR3, and TLR4 expression, inducing activation of infected macrophages, whereas infection with L. donovani suppresses the TLR2–NF-κB–mediated pro-inflammatory cytokine response." (PMID 24098824, 2013). "Here we report that, following low dose aerosol infection with Mtb, mice lacking TLR2 (TLR2KO), in comparison with wild type (WT) mice, exhibit enhanced cellular infiltration and inflammation in the lungs, and fail to stably control bacterial burden during chronic infection." (PMID 23785280, 2013). "Lastly, infection of VSMCs by C. pneumoniae induces the production of IL-6, basic fibroblast growth factor (bFGF), and MMP, via NF-κB activation, contributing to plaque destabilization, and MCP-1 release through toll-like receptor 2 (TLR-2), promoting monocyte migration into intima." (PMID 23877837, 2013). "Furthermore, TLR2, but not TLR4, has been shown to be essential for efficient internalization of Aspergillus fumigatus conidia, since infection of macrophages deficient in TLR2 rendered reduced conidial cell entry." (PMID 24312679, 2013). "Phagocytosis of the infecting Mtb and upregulation of TLR-2 and TLR-4 would result in the early production of IL-12, thereby contributing to the activation of lymphoid cells, consistent with our observation of elevated IL12B expression at 2 weeks post-infection." (PMID 23448601, 2013). "In contrast, the lack of TLR2 and unrestricted function of Nods in TLR2-/- mice could lead to uncontrolled IOE infection and immunopathology, which is consistent with the phenotype of IOE-infected Nod2-/- mice." (PMID 23526993, 2013).
infection (continued). "In accordance, TLR-2-/- BMM did not increase Fth1 mRNA expression upon infection." (PMID 24349383, 2013). "Similarly, infection of Socs3fl/fl LysM cre BMM with BCG or stimulation with Pam3CSK4, an agonist for TLR2, a receptor that plays a prominent role in the initiation of responses against M. tuberculosis, led to higher NO and iNos mRNA levels compared to controls." (PMID 23853585, 2013). "Despite an earlier study demonstrating rYopJ activation of TLR-2 signaling in macrophages, in vivo studies employing both Drosophila and macrophage models of infection clearly demonstrated that native YopJ indeed activated the NF-κB signaling but not the TLR-2 signaling pathway." (PMID 24199174, 2013). "In addition, the experiments performed confirm previous findings concerning the lack of significant contribution of TLR4 and TLR2 with regard to spleen (and liver) infection, but reveal their significant contribution preventing lung infection." (PMID 22973560, 2012). "In line with this, the immunoregulatory role for TLR2 reported during the acute infection could be explained by the fact that the suppressive function of Tregs is directly controlled by the triggering of TLR2 but not TLR4 or TLR9." (PMID 21869919, 2012). "We then examined how the absence of TLR2 leads to more severe disease and infection." (PMID 22724018, 2012). "Finally, The engagement of PKR and the subsequent production of type-1 IFNs and of superoxide dismutase (SOD-1) were necessary for effective parasite growth and dependent on TLR2, indicating that this TLR is required for the successful infection of macrophages by L. amazonensis." (PMID 22523644, 2012). "Thus, the absence of TLR2 promotes enhanced innate responses (NK cell and neutrophil responses that may be driven by increased IL-17 expression), which are associated with increased severity of Chlamydia respiratory disease and infection in our early life infection model." (PMID 22724018, 2012). "Thus, the absence of TLR2 increases the recruitment of activated of CD8+ T-cells in the lung, which is associated with increased severity of Chlamydia respiratory disease and infection in early life." (PMID 22724018, 2012). "Thus, the absence of TLR2 suppresses phagocytosis by neutrophils and provides a mechanism whereby the absence of TLR2 leads to increased severity of Chlamydia respiratory disease, infection and inflammatory responses in early life." (PMID 22724018, 2012). "In contrast, HEK293-TLR2 and HEK293-TLR5 cells were highly competent for inducing the secretion of IL-8 and TNF-α cytokines in a cagPAI-independent manner, suggesting that the expression of TLR-2 or TLR-5 has profoundly changed the capability to trigger pro-inflammatory signalling upon infection." (PMID 21573018, 2011). "Thus, in contrast to the in vitro infection, TLR2 expression was not required for the induction of cytokines in vivo following intranasal challenge." (PMID 21695078, 2011). "We reasoned that since TLR2−/− mice had reduced numbers of lung Tregs at baseline, and did not increase their Treg numbers 5 days after infection, they should be able to develop sensitization even at day 10 after infection if Treg played a critical role in this event." (PMID 21695198, 2011). "Identical to these published findings we show here, that in C. pneumoniae-infected TLR2/4 double-deficient BMDM IFNγ only weakly up-regulated the expression of iNOS and failed to induce the secretion of NO, since the infection of these cells with C. pneumoniae did not induce NF-κB." (PMID 22096480, 2011). "Altogether, the modification of TLR2 and MAPK signalling pathways might be responsible for a higher uptake of bacteria by phagocytes, and therefore might contribute to the more efficient clearance of the infection in the resistant line." (PMID 21527017, 2011).
infection (continued). "We showed that innate TNF-α responses and TNF-α: IL-10 ratios upon TLR2 stimulation of PBMCs were significantly higher in S. haematobium-infected children compared with those without infection, in the face of enhanced regulatory adaptive responses to schistosomal antigens." (PMID 21931706, 2011). "In this study, retinal TLR2 mRNA expression did not increase during infection." (PMID 22163046, 2011). "As we predicted, we observed that TLR2−/− mice can develop allergic sensitization when the antigen is introduced initially both at day 5 and day 10 after infection, while WT mice is sensitized only when antigen is given at day 5 but not day 10 after infection." (PMID 21695198, 2011). "However, we found that neither TLR2 knockout nor TLR2/TLR4 double knockout mice exhibited differences in survival compared to WT mice using this infection model (unpublished data)." (PMID 22039448, 2011). "However, the increase of macrophages and total DCs, as well as the new generation of inflammatory macrophages observed early after infection, in wild-type mice, were absent or significantly reduced in TLR2−/− mice." (PMID 21935459, 2011). "Numerous in vitro studies document the activation of TLR2 by Gram-positive ligands, but these models may not represent the in vivo environment during infection." (PMID 22163046, 2011). "When TLR2−/− and C57BL/6 mice were intravenously infected with 1.5×106 yeasts, it was found that fungal cells are able to reach the bone marrow and the amount of yeasts recovered from this site at day 3 post-infection was roughly 6000 colony-forming units (CFUs) per animal." (PMID 21935459, 2011). "TLR2-mediated recognition of mycoplasma lipoproteins, derived from several mycoplasma strains, is well documented in the literature, but there are little or no studies demonstrating the ability of TLR2 to recognize infecting organisms or determining the outcome of this interaction during infections." (PMID 20505832, 2010). "For example, patients with dampened TLR2 signaling in the airways may not be able to generate sufficient amount of SPLUNC1 in response to an infection, and fail to eliminate the invading pathogen and resolve excessive inflammatory response." (PMID 21054862, 2010). "In addition to live VV, UV-VV can also activate NK cells via TLR2, suggesting that the stimulation of TLR2 on NK cells by VV is independent of newly synthesized viral gene products after infection." (PMID 20300608, 2010). "Evidence for evolutionary conservation of this regulation in additional primate lineages would provide strong evidence that the TLR2/1-vitamin D-cathelicidin pathway evolved as a biologically important immune response mechanism protecting human and non-human primates against infection." (PMID 19607716, 2009). "Evidence for the evolutionary conservation of this regulation in additional primate lineages would provide strong evidence that the TLR2/1-vitamin D-cathelicidin pathway evolved as a biologically important immune response mechanism for protecting human and non-human primates against infection." (PMID 19607716, 2009). "Moreover, signaling through TLR2 does not depend exclusively on TLR1 or TLR6 during F. tularensis LVS infection." (PMID 19936231, 2009). "Remarkably, whereas S. pneumoniae PLN did not further grow in the lungs of WT mice from 24 h after infection onward, which is in line with a previous investigation, the bacterial load increased more than 10-fold in lungs of TLR2 KO mice between 24 and 72 h after inoculation." (PMID 17711480, 2008). "To obtain further insight into the involvement of TLR2 and TLR4 in the inflammatory response after infection with B. pseudomallei, we semiquantitatively scored lung histology slides generated from WT, TLR2 KO, and TLR4 KO mice at various time points after infection." (PMID 17676990, 2007).